LGALS7B (galectin 7B)
Description:
Could be involved in cell-cell and/or cell-matrix interactions necessary for normal growth control. Pro-apoptotic protein that functions intracellularly upstream of JNK activation and cytochrome c release.
Synonyms: GAL7; HKL-14; PI7
Tractability: Small molecule: a structure with a bound ligand is known; a high-quality ligand is known. Antibody: UniProt places it where antibodies can reach, with high confidence; its Gene Ontology location is reachable by antibodies, with medium confidence. PROTAC: a small molecule that binds it is known.
Target class: Other cytosolic protein
Gene: Protein-coding gene on chromosome 19 (38,789,200 to 38,791,754, forward strand). Ensembl gene ENSG00000178934.
Subcellular location: Cytoplasm; Nucleus; Secreted
Pathways (Reactome):
Developmental Biology: Differentiation of Keratinocytes in Interfollicular Epidermis in Mammalian Skin
Gene Ontology:
Molecular function: protein binding; carbohydrate binding
Biological process: heterophilic cell-cell adhesion
Cellular component: extracellular exosome; extracellular region; cytoplasm; nucleus
Genetic constraint (gnomAD): Loss-of-function variants: 1 observed, 4.86 expected, observed/expected ratio (o/e) 0.21, 90% interval 0.072 to 0.97. That is too few expected variants to judge how well the gene tolerates losing a copy. Missense variants: 17 observed, 64.7 expected, observed/expected ratio (o/e) 0.26, 90% interval 0.18 to 0.39. Synonymous variants: 7 observed, 26.31 expected, observed/expected ratio (o/e) 0.27, 90% interval 0.15 to 0.5.
Homologues: Orthologues: mouse Lgals7 (78% identical), rat Lgals7 (64% identical), Drosophila melanogaster galectin (34% identical), zebrafish lgals3b (33% identical), Caenorhabditis elegans lec-3 (32% identical), Caenorhabditis elegans lec-1 (31% identical), Caenorhabditis elegans lec-6 (31% identical), Caenorhabditis elegans C27C7.5 (29% identical), zebrafish si:dkey-95h12.2 (29% identical), Caenorhabditis elegans F40H6.5 (28% identical), Caenorhabditis elegans lec-12 (28% identical), Caenorhabditis elegans lec-8 (27% identical), and 12 more. Paralogues in human: LGALS7 (100% identical), LGALS4 (39% identical), LGALS9 (38% identical), LGALS9B (38% identical), LGALS9C (38% identical), LGALS8 (35% identical), LGALS1 (32% identical), LGALS3 (32% identical), LGALS16 (29% identical), CLC (28% identical), LGALS13 (28% identical), LGALS14 (28% identical), and 4 more.
Diseases named in the same sentence as LGALS7B in open-access papers:
LGALS7B is named in the same sentence as 12 diseases in open-access papers, as found by Europe PMC text mining. Sharing a sentence is not in itself a finding about the gene and the disease. The quoted sentences say what the papers report.
breast carcinoma (2 papers, 2015 to 2024). "Another remarkable upregulated gene was LGALS7B, a basal cell marker which enhances metastasis to the lungs and bones in breast cancer." (PMID 25391423, 2015).
cancer (5 papers, 2023 to 2025). A tumor composed of atypical neoplastic, often pleomorphic cells that invade other tissues. "In cutaneous SCC, that originates from keratinocytes in the skin, we observed the expression of galectin-7 genes (LGALS7 and LGALS7B) in both normal and cancer cells." (PMID 38384845, 2024). "That is the case for genes encoding for galectin-7 (LGALS7 and LGALS7B), highly expressed in SCC, that were found to be downregulated in cancer cells from cutaneous SCC but upregulated in the ones from esophagus SCC." (PMID 38384845, 2024). "LGALS7B is known to play role in several types of carcinomas, and the expression shows a high mean in the squamous epithelium region but a high variance in the stroma region." (PMID 37285319, 2023). "Galectin-7 has a tumor-promoting function in diverse cancer types, including HNSCC25–27, therefore, it is plausible that the aggressive feature of CC1 might be associated with the expression of p-EMT and LGALS7B." (PMID 36828832, 2023).
tumor (3 papers, 2017 to 2025). "The identification of malignant cells in the fibroblast subpopulation of Galectin 7B and CXCL8 suggests that abundance in tumor tissue is associated with poor prognosis." (PMID 41403916, 2025). "In addition, we identify the cell type subsets of the Galectin 7B (LGALS7B)-expressing malignant cells and CXCL8-expressing fibroblasts, demonstrating that their abundance in tumor tissue is associated with unfavorable prognostic outcomes." (PMID 36828832, 2023). "Genes up-regulated in cells from tumor specimens grown under CRC culture conditions are enriched with markers for lung basal cells such as TP63 (> 60 fold), podoplanin (PDPN, > 36 fold), cytokeratin genes KRT6A (> 729 fold), KRT6B (> 98 fold), and adhesion molecules LGALS7B (> 200 fold)." (PMID 28052041, 2017).
LGALS7B also shares sentences with these, for which no sentence is quoted: brain cancer (1 paper); leukemia (1); liver cancer (1); lung adenocarcinoma (1); lung carcinoma (1); melanoma (1); ovarian carcinoma (1); squamous cell carcinoma (1); uveal melanoma (1).